INS (insulin)
Diseases named in the same sentence as INS in open-access papers (continued):
Sharing a sentence is not in itself a finding about the gene and the disease.
cancer (continued). "Metformin exerts both direct (insulin-independent) and indirect (insulin-dependent) effects on cancer cells, which may interact with each other." (PMID 39796190, 2025). "Importantly, by lowering systemic insulin levels, metformin targets a critical driver of tumor growth in insulin-responsive cancers." (PMID 41347072, 2025). "Furthermore, insulin pathway-dependent proteinss such as mTOR, AKT, and PI3K are associated with metabolic homeostasis, cell cycle regulation, proliferation, cancer, and longevity." (PMID 41181393, 2025). "Nevertheless, the available data are inconclusive, with several findings indicating that insulin may have an adverse effect on the clinical course, resulting in a shorter cancer-specific survival." (PMID 39976819, 2025). "Metformin exerts both insulin-independent and insulin-dependent effects on cancer cells." (PMID 40563926, 2025). "Therapeutic proteins such as insulin and monoclonal antibodies (mAbs) have become an essential part of the modern healthcare system and play a crucial role in the treatment of various diseases including cancer and autoimmune disorders." (PMID 40060006, 2025). "miR-375, initially identified as a pancreatic islet-specific miRNA regulating insulin secretion, and findings highlight that miR-375 is significantly downregulated in various cancers and acts as a suppressor of key cancer hallmarks by targeting critical oncogene." (PMID 40076805, 2025). "Similarly, global transcriptomic and biochemical analyses indicate that the activity of the insulin/IGF‐1–AKT–mTOR pathway is diminished in the cachectic muscle of cancer patients and animal models." (PMID 39764565, 2025). "Excess adipose tissue may promote cancer cell proliferation and metastasis through mechanisms involving insulin resistance and IGF-I release, and it may exert a direct stimulatory effect on thyroid cell growth." (PMID 40933379, 2025). "However, initiating insulin in cancer patients undergoing chemotherapy poses challenges due to their frailty and the burden of cancer itself, in addition to the fear of self-injecting insulin." (PMID 40426928, 2025). "The most investigated genes were those implicated in neuroendocrine stress responses; dopamine, norepinephrine, and serotonin signalling; apoptosis; insulin secretion; neuroplasticity; reproduction; foetal growth; and cancer (e.g. MAOA, BRSK2, ADCYAP1, BDNF, DRD2, IGF2, H19)." (PMID 41070359, 2025). "Therefore, the reduction of both insulin and glucose levels by metformin affects the proliferation rate of cancer cells both directly and indirectly." (PMID 40678416, 2025). "Additionally, exercise mitigates cancer-related symptoms like fatigue, improves insulin sensitivity, and counteracts metabolic issues such as cachexia." (PMID 40487761, 2025). "Elevated insulin and IGF-1 are associated with increased cell growth and proliferation, while metformin’s influence on these pathways parallels CR’s ability to reduce cancer-promoting signals." (PMID 39940361, 2025). "Additionally, metabolites, particularly AAs, are involved in the biological processes of tumorigenesis, cancer cell invasion, cancer stem cell pluripotency, insulin sensitivity, epigenetic regulation, and other cellular processes." (PMID 41008653, 2025). "In addition to regulating glucose metabolism in normal cells, insulin/IGF also affects cancer cell metabolism by activating the Ras/MAPK/Erk pathway." (PMID 39948335, 2025). "Moreover, insulin was shown to induce the migration ability of cancer cells, contributing to metastasis." (PMID 41374092, 2025). "For instance, NAM has been reported to decrease insulin sensitivity and inhibit poly(ADP‐ribose) polymerases, which may affect genome stability and cancer risk." (PMID 39931736, 2025). "The effect of insulin has been rather exploited in cancer, but glucagon has been passed over." (PMID 40649254, 2025).
cancer (continued). "The main findings from this observational analysis are significant associations between aerobic physical activity (as measured by MVPA or steps), device-based tracking during six months after surgery, and VO2max, cardiac output, and metabolic biomarkers (insulin and leptin) in cancer survivors." (PMID 40783771, 2025). "In fact, although there are no direct studies linking IF to reduced cancer risk in humans, its effect has been explored through its impact on tumor-related factors, such as insulin, glucose, IGF-1, leptin levels, adiponectin and weight loss." (PMID 39940361, 2025). "Additionally, adiponectin enhances insulin sensitivity and reduces inflammation, both of which are critical in mitigating the obesity-cancer link." (PMID 40040878, 2025). "In particular, tirzepatide may increase the synthesis of insulin, IGF-1, IGF-2, and their binding proteins—factors that have been linked to elevated cancer risk, especially in patients with prior pancreatic injury." (PMID 41310711, 2025). "Even less is known about the mechanisms of metformin in cancer, but both direct and indirect effects on cancer cells have been suggested, including a lowering of insulin levels which may suppress cancer cell proliferation." (PMID 40336178, 2025). "Monami and associates, in 2011, observed that another compelling argument for continuing metformin therapy among individuals receiving insulin treatment may be a reduced likelihood of malignant tumors." (PMID 40572709, 2025). "Notably, metformin has shown antitumor effects in epidemiological studies, further linking insulin pathways, microbiota, and cancer biology." (PMID 40564016, 2025). "Metformin lowers insulin levels and IGF-1 signaling, which can reduce the risk of cancer." (PMID 39940361, 2025). "Aging and cancer induce changes in cytokines and noncoding RNAs, leading to unfavorable fat deposition and accumulation, persistent low‐grade inflammation, and impairments in lipolysis, glucose uptake, and insulin sensitivity." (PMID 39764565, 2025). "At the clinical level, previous meta-analyses have provided preliminary evidence that exercise can improve common metabolic disturbances in cancer patients, including blood glucose, insulin, and triglycerides, as well as inflammatory markers such as IL-6, C-reactive protein (CRP), and TNF-α." (PMID 40895542, 2025). "As we know, Vitamin D participates in several physiological processes, includes the regulation of arterial blood pressure, modulation of immune responses, regulation of insulin secretion, protection against certain cancers, renoprotection, and other beneficial effects." (PMID 40308226, 2025). "In addition to being a regulator of glucose metabolism, insulin is an anabolic hormone involved in the promotion of cancer progression by activating the PI3K/AKT pathway." (PMID 39941833, 2025). "The findings also imply that insulin use could potentially promote cancer growth, underscoring the importance of considering cancer risk when selecting antidiabetic therapies." (PMID 39777709, 2025). "Given that BAT is widely known to reduce whole-body blood glucose and insulin levels in humans, we reason that the CRISPRa-modulated adipose organoids could also reduce cancer progression by lowering plasma insulin levels." (PMID 39905264, 2025). "Metabolic oscillations are a widespread phenomenon and occur not only in glycolysis of fermenting yeast cells but also in glycolysis of cancer cells, in pancreatic β-cells in connection with pulsatile insulin secretion, as well as in muscle cells and human neutrophils." (PMID 40603986, 2025). "Epidemiological evidence links PFAS to a broad spectrum of health concerns, including thyroid dysfunction, immune system impairments, liver disease and cancer, disturbances in lipid and insulin levels, kidney disease and cancer, reproductive and developmental issues, and impacts on neurodevelopment." (PMID 39997367, 2025).
cancer (continued). "Its suppression by insulin via downregulation of HNF4α links hepatic metabolic status to systemic hormonal control, establishing SHBG as a key mediator at the intersection of metabolic dysfunction, hyperinsulinaemia, and cancer risk." (PMID 41586225, 2025). "Notably, two distinct insulin-expressing cancer cell populations were captured in all three samples." (PMID 40438247, 2025). "Research has shown that metabolic abnormalities such as insulin resistance and chronic inflammation may promote cancer cell proliferation and invasion by affecting cellular energy metabolism and signal transduction." (PMID 40191429, 2025). "Hence, these findings highlight the critical role of IRS1 and IRS2 neddylation in facilitating cancer cell migration under conditions of insulin signaling dysfunction." (PMID 38272982, 2024). "In this study, we sought to determine whether the addition of insulin would confer any potential proliferation and/or survival advantages to cancer cells being treated with ARG." (PMID 38374190, 2024). "Insulin, as a peptide hormone that stimulates tissue accretion, has a cancer-promoting effect." (PMID 38468310, 2024). "Lower post-MBS insulin and IGF-1 levels likely reduce cancer risk." (PMID 39594685, 2024). "The marked reduction in the incidence of certain types of cancer, such as those of the liver and pancreas, may be explained by the known fact that insulin resistance plays a pivotal role in their growth." (PMID 38675438, 2024). "Further investigations into the involvement of this signaling axis in mediating CB1-biased effects may have important implications for pharmaceutical development and uncover new mechanisms regarding insulin signaling and cancer metastasis." (PMID 38534324, 2024). "This is consistent with the metformin anti-tumoral effects which are not limited to its direct effects on cancer cells, but also in changes on the systemic level due to metformin may exert antitumor effects by reducing insulin levels." (PMID 39026155, 2024). "In addition, the effect of exercise on inflammatory, insulin, and metabolic pathways involved in physical activity and cancer survival is hypothesized, however, current evidence is limited to select high risk populations, or to monitor the biologic response to exercise among cancer survivors." (PMID 38926526, 2024). "Thus, alteration in genes involved in the insulin signaling pathway can influence cancer development." (PMID 39410536, 2024). "Firstly, the high levels of insulin in IR individuals may promote cancer via abnormal stimulation of multiple cellular signaling cascades, i.e. the Ras signal pathway, enhancing growth factor-dependent cell proliferation or directly affecting cell metabolism." (PMID 38300233, 2024). "Suppression of insulin signaling in tissues has been observed in pathologies, such as cancer." (PMID 38566182, 2024). "The association of circulating levels of IGF-1, IGFBPs, and insulin also supports their roles in cancer but is not always consistent with the molecular data." (PMID 38928185, 2024). "In this regard, LCDs, which can impact insulin levels, have been proposed for cancer treatment." (PMID 38523829, 2024). "Since the combination of ARG and insulin showed differential ARG uptake patterns between the cancer cell lines, we were interested to determine if that would have any impact on cell proliferation and most importantly, if cells were able to recover following ARG treatment." (PMID 38374190, 2024). "After cancer develops, its growth may be stimulated by other factors, such as endogenous insulin and lipids." (PMID 38392069, 2024).
cancer (continued). "While cellular senescence is thought to be a protective mechanism against cancer, its presence in adipose tissue can lead to numerous issues, such as impaired fat cell formation, inflammation, abnormal adipocytokine production, and insulin resistance." (PMID 38728252, 2024). "Insulin also binds to insulin-like growth factor-1 receptor due to highly similar structure and activates the downstream signaling pathway in prostate cells, thereby proliferating cancer cells." (PMID 39781138, 2024). "Clinical studies suggest that a KD may inhibit cancer cell growth through mechanisms involving reduced glucose availability, increased insulin sensitivity, elevated levels of KBs, and potential weight loss, thus altering metabolic pathways." (PMID 39064705, 2024). "Decreased levels of insulin and IGF-1 are associated with exercise and may contribute to the decreased risk of cancer with exercise." (PMID 38928185, 2024). "An increase in insulin may also reduce the inhibitory effects of IGFBP‐1 on cancer cell growth and migration." (PMID 38477501, 2024). "Additionally, treatments like oral insulin secretagogues (e.g., SUs) showed favorable impacts on certain cancers, highlighting the complex and context-dependent role of insulin in cancer dynamics." (PMID 39595655, 2024). "Insulin may induce cancer growth by its mitogenic and antiapoptotic effects, as is observed in the case of breast and prostate cancers." (PMID 38397072, 2024). "Moreover, insulin, which is structurally similar to IGF-1, is also related to cancer risk and outcomes, with hyperinsulinemia linked to a greater risk of cancer and cancer-related death." (PMID 38928185, 2024). "In T2DM insulin levels are high and may confer a higher cancer risk to these patients through its mitogenic effects, and, by the same token, anti-diabetic medications that lower insulin levels may be beneficial in cancer treatment." (PMID 38835644, 2024). "Metformin indirectly affects cancer cells by decreasing the glucose and insulin levels in the body." (PMID 38612893, 2024). "This review presents an examination of essential phytochemicals found in plants and foods within Mexican agrobiodiversity that have shown promising anti-cancer and anti-diabetic properties, including their roles as antioxidants, insulin sensitizers, and enzyme inhibitors." (PMID 39767118, 2024). "Furthermore, DGUOK‐AS1 and SIX1 is stimulated by insulin, a secreted protein related to lipogenesis and cancer, but miR‐145‐5p is inhibited by insulin." (PMID 39258807, 2024). "The pathways exclusively represented by the upregulated genes at 3 h treatment include ‘glycolysis/gluconeogenesis’, ‘bisphenol degradation’ and that represented by upregulated genes at 6 h treatment include ‘proteoglycans in cancer’, ‘lysine degradation’, ‘insulin signaling pathway’." (PMID 38351213, 2024). "A cohort study specifically examined the effects of metformin, insulin, and sulfonylureas on the risk of developing GC and found that the latter two drugs actually increased the risk of GC by elevating the levels of IGF-1, which promotes cancer cell survival." (PMID 38612893, 2024). "Some ADRs, like neoplasms (cancers), may take years to manifest, making it difficult to establish a direct link between insulin use and the development of such conditions." (PMID 39457586, 2024). "Second, insulin and insulin-like growth factor-1 are known to be involved in cancer progression." (PMID 38523829, 2024). "We conclude that a combined intervention of physical activity/exercise and diet/nutrition may decrease body weight, fat mass, insulin levels, and inflammation and improve lipidemic profiles in cancer patients and survivors." (PMID 38892682, 2024). "Furthermore, the insulin signaling cascade contains key components including RAS, RAF, PI3K, and AKT which are frequently mutated in different types of cancer." (PMID 39410536, 2024).
cancer (continued). "Finally, there was a strong downregulation of PPARγ gene, essential for insulin sensitization and glucose uptake, potentially impairing multiple metabolic pathways utilized by cancer cells for growth and proliferation." (PMID 38674023, 2024). "In cachectic cancer patients, the disturbed insulin-stimulated anabolic fluxes may shunt substrates to support the tumor anabolism." (PMID 38450189, 2024). "In addition, it has been discovered that the ketogenic diet can change insulin-related signaling molecules, such as C-peptide or IGF-1, which have been associated with an increased risk of cancer." (PMID 39338183, 2024). "In addition to increasing cancer risk through IGF-1, insulin also influences carcinogenesis and progression by lowering sex hormone-binding globulin (SHBG) levels." (PMID 39290325, 2024). "ADT is an effective cancer treatment, but it facilitates significant declines in muscle mass and adverse health outcomes important to mCSPC survivors, such as fatigue, and reductions in physical function, independence, insulin sensitivity, and QoL." (PMID 38637770, 2024). "However, resistance exercise seems to modulate insulin sensitivity in cancer patients by preserving or enhancing lean body mass." (PMID 39062775, 2024). "While some cancer sites showed a higher risk for glargine users and others lower risk compared to non-glargine insulin users, these risk estimates were not statistically significant." (PMID 39434861, 2024). "The growth of cancer cells is effectively induced by insulin." (PMID 38707901, 2024). "Additionally, there was a notable downregulation of PPARγ, which plays a crucial role in insulin sensitization, glucose uptake, and enhancement of energy metabolism in HT-29 cancer cells." (PMID 38674023, 2024). "However, increased visceral adipose tissue significantly increases insulin resistance, producing adverse metabolic effects that can increase cancer mortality." (PMID 39574952, 2024). "It has been postulated that the impact on the capacity for insulin secretion might indicate the effectiveness of ICI in the treatment of patients with cancer." (PMID 39722806, 2024). "The influence of insulin and IGFs on cancer growth has been widely studied." (PMID 38392069, 2024). "Additionally, the extended fasting time in TRE regimens is expected to reduce the exposure to cancer-promoting growth factors like insulin and IGF-1." (PMID 39458471, 2024). "The KEGG data suggests that the role of eEF2K in cancer pathogenesis may be related to the GnRH, neurotrophin, insulin, and MAPK signaling pathways." (PMID 39592671, 2024). "The abnormal expression identified may be involved in promoting cancer by amplifying the effects of elevated insulin levels, as commonly seen in obese individuals and type 2 diabetic patients." (PMID 38331804, 2024). "The activation of IR as well as IGF-1R/IR hybrid receptors by insulin may contribute to cancer growth, leading to resistance to IGF-1R inhibition." (PMID 39335147, 2024). "The role of insulin in cancer development and progression is interesting." (PMID 38392069, 2024). "These pathways are driven by insulin and are thought to play a role in the development of cancer." (PMID 39338183, 2024). "Insulin is proposed to be an oncogenic factor and contributes to the progression of cancer." (PMID 38397072, 2024). "Usually I have to use insulin to maintain my blood sugar and the doctor also told me to supplement pancreatic enzymes, which are good for me to control my disease, but can they fight cancer?" (PMID 37655196, 2023). "Several studies have suggested that the insulin signaling pathway plays an important role in the development and progression of cancer, as it is involved in cell growth and proliferation processes due to its capacity to stimulate DNA synthesis in various tissues." (PMID 36975518, 2023).